IL10 (interleukin 10)
Diseases named in the same sentence as IL10 in open-access papers (continued):
Sharing a sentence is not in itself a finding about the gene and the disease.
acute GVHD (17 papers, 2009 to 2026). "The STAT6-driven Th2 pathway and immune regulatory cytokines (IL10, TGFβ) are associated with the regulation of Th1 cytokine IFNγ production and the mitigation of acute GVHD, the severity of which is more dominantly driven by Th1 cytokines." (PMID 39796136, 2024). "Recipients of a graft with a single nucleotide polymorphism (SNP) in the donor IL-10 gene promoter region were found to be protected against the development of grade II–IV acute GVHD." (PMID 36555525, 2022). "Recipients of a graft carrying the -1082GG IL10 gene promoter region variant had a three-fold lower incidence of grade II–IV acute GVHD compared to IL10-1082AA graft recipients (SHR = 0.25, p = 0.005)." (PMID 36555525, 2022). "In the third stage, cellular and inflammatory factors are released, including TNF-α, IL-1, IL-6, IL-10, IL-12, which underlie the clinical manifestations of acute GVHD." (PMID 23802653, 2013). "The difference in genotypic IL-10 production between patient and donor in combination with patient IL-10Rβ A/A genotype predisposed strongly to acute GvHD (OR = 7.15, p = 0.000023)." (PMID 19409109, 2009). "IL-10Rβ A/A strongly predisposed to acute GvHD when patient and donor IL-10 production level differed, but protected from chronic GvHD when patient and donor had similar IL-10 production level." (PMID 19409109, 2009). "In conclusion, higher numbers of NK‐14 cells are strongly correlated with a reduced risk of acute GVHD and our finding that such cells express high levels of IL‐10, and are targeted to lymphoid and peripheral tissue, provides a direct mechanism for this association." (PMID 28944953, 2018). "Moreover, they have demonstrated that the mechanism of B cells in suppressing GVHD is directly related to IL-10 as IL-10−/− mice developed more severe acute GVHD than recipient mice in which B cells are wild type." (PMID 25002862, 2014). "A polymorphism in the TNF-α gene was demonstrated to increase incidence of severe acute GHVD, but polymorphisms in IL-10, which was considered as suppressing TNF-α, IL-1, and other inflammatory cytokines, was demonstrated with the ability to decrease incidence of acute GVHD." (PMID 23802653, 2013). "Finally, we analyzed methylation in IFN-γ, FASL, IL-10, and PRF1 and found association with the severity of the acute graft-versus-host disease." (PMID 23451113, 2013). "In contrast, elevated IL-6, IL-17A, PAI-1, IL-10, CX3CL1, CXCL1, and CCL4 levels were prognostic for quiescent cGVHD compared with patients with resolved acute GVHD only." (PMID 41798937, 2026). "IL-10 is also a known suppressor of CD8+ T-cell activity, with IL-10 overproduction having been shown to suppress acute GVHD pathogenesis." (PMID 36555525, 2022). "Paradoxically, IL-10, which is thought to inhibit the synthesis of inflammatory cytokines such as IL-8 and TNF-α, was elevated in patients with acute GVHD in our results." (PMID 28881843, 2017). "To determine whether GMSCs could suppress acute GVHD through controlling cytokine production by staining with IFN-γ, IL-17, IL-4, TNF-α, IL-2, and IL-10, we detected the production of cytokines after injecting 15 days." (PMID 30622237, 2019).
Fever (17 papers, 2006 to 2025). Body temperature elevated above the normal range. "Experimental infection with ORF1 and ORF71 deletion mutants revealed a brief period of pyrexia, low virus shedding, and decreased cytokine response (IFNα, IL-10, and soluble CD14); however, they had comparable viremia to Ab4-wt." (PMID 32911663, 2020). "Under fever conditions, different kinds of endogenous anti-inflammatory cytokines are induced, both pyrogenic such as IL-1α and -β, IL-6, IL-8 and interferon-γ (IFNγ), and antipyretic, such as IL-10 and TNFα." (PMID 23166650, 2012). "IL-10 was also reported to have an antipyretic effect in LPS-induced fever in mice." (PMID 24049647, 2012). "Thus, fever suppresses IL‐1β and IL‐10 gene expression in Mtb‐stimulated MDM." (PMID 40667841, 2025). "MP, a common exogenous pyrogen, stimulates the production of numerous inflammatory factors in the body, including IL-6, IL-10, and IFN-γ, potentially leading to persistent fever or even hyperpyrexia." (PMID 40656192, 2025). "Regardless immunoglobulin profile, all OROV fever patients presented higher levels of CXCL8, and IFN-α and lower levels of TNF and IL-10 at baseline as compared to healthy donors (HD)." (PMID 31784575, 2019). "Hay fever cases exhibiting IL4R Q576R GG, IL10(-819) TT or IL18(-137) CC genotype had also increased total IgE levels, although not significant due to low statistically power." (PMID 16759385, 2006). "Kidney tissues from fever seahorses exhibited significantly higher mRNA expression levels of tnf-α, il-6, ifn-g, and il-10 compared to the no-fever group (p < 0.05)." (PMID 40508975, 2025). "In no-fever individuals, the absolute copy number of measured il10 cytokine mRNAs in the spleen increased slightly at 48 and 72 hpi." (PMID 34445566, 2021). "However, in the context of our model using a virulent Mtb strain (H37Rv), a moderate reduction in IL‐10 expression by fever did not affect the amount of Mtb recovered from infected MDM." (PMID 40667841, 2025). "HMGB1 together with IL-1β, IL-8, IL-10, and MCP-1 can serve as biomarkers to identify children with ALL and fever or SIRS who should not receive antimicrobial treatment because the origin of their fever is not due to an infectious agent." (PMID 40868835, 2025). "The results showed that OROV fever patients presented higher levels of CXCL8 and IFN-α (pink background) and lower levels of TNF and IL-10 than HD (blue background), regardless of antibody profile at baseline." (PMID 31784575, 2019).
gestational diabetes (17 papers, 2012 to 2025). Carbohydrate intolerance first diagnosed during pregnancy. "While Acinetobacter species are recognized as opportunistic pathogens colonizing various human niches (e.g., skin, mucosa, blood), their abundance has also been positively associated with IL-10 in the placental microbiota of women with gestational diabetes." (PMID 40871439, 2025). "An increase in the TNF-α/IL-10 ratio potentially causes early and late pregnancy complications, mostly implantation failure, fetal loss, hypertensive syndromes, and gestational diabetes." (PMID 37887854, 2023). "Further studies are needed to verify the mechanisms involved in changes in serotonin and IL-10 levels in blood and urine and the modulatory role of these bioactive components in gestational diabetes associated with pregnancy-related urinary incontinence." (PMID 38138954, 2023). "Therefore, more research is needed to confirm the processes underlying alterations in blood and urine levels of serotonin and IL-10 and the modulatory functions of these bioactive elements in gestational diabetes, which is associated with pregnancy-related UI." (PMID 39538179, 2024). "The current study has demonstrated that the cytokine IL-10 was reduced in plasma and increased the excretion in the urine of pregnant women with gestational diabetes and urinary incontinence." (PMID 38138954, 2023). "Based on the data from the present study, it can be concluded that pregnant women with gestational diabetes mellitus and pregnancy-specific urinary incontinence experience decreased hemoglobin, hematocrit, serotonin, and IL-10 in their blood." (PMID 38138954, 2023). "Women with gestational diabetes have higher concentration of inflammatory cytokines including IL-6, IL-10, and TNF-α compared with healthy pregnant women." (PMID 29385062, 2018). "Notably, pregnant women with gestational diabetes and UI had higher levels of IL-10 in their urine, and a positive correlation was observed between plasma and urine levels in this group." (PMID 39538179, 2024). "However, the influence of IL-10 and serotonin on pregnancy-specific urinary incontinence in pregnant women with gestational diabetes mellitus is not fully understood." (PMID 38138954, 2023). "Thus, this study evaluated the influence of serotonin and IL-10 on blood and urine viscosity in pregnant women with gestational diabetes mellitus and pregnancy-specific urinary incontinence." (PMID 38138954, 2023). "This research highlights the potential of serotonin and IL-10 in reducing the blood viscosity of pregnant women with gestational diabetes and pregnancy-specific urinary incontinence and maintaining values similar to those found in the blood of normoglycemic women." (PMID 38138954, 2023). "However, after childbirth, the secretion of adiponectin and anti-inflammatory cytokines such as IL-10 is increased, which eventually allows the mother to overcome her gestational diabetes condition." (PMID 37026009, 2023). "In addition, hypomethylation of IL-10 in maternal blood and increased plasma concentrations of IL-10 before delivery were noted in women with gestational diabetes." (PMID 35600817, 2022). "To further validate our dataset, we investigated the relationship between interleukin-10 (IL-10) and gestational diabetes mellitus (GDM)." (PMID 40996707, 2025). "Serotonin and interleukin 10 (IL-10) may play a role in gestational diabetes mellitus." (PMID 38138954, 2023). "Whether polymorphisms in tumor necrosis factor-α (TNF-α), interleukin-6 (IL-6), interleukin-10 (IL-10) or adiponectin (ADIPOQ) influence the risk of gestational diabetes mellitus (GDM) or not remain inconclusive." (PMID 32963590, 2020). "As pregnancy develops, high TNF-α concentrations have been related to the development of preeclampsia and gestational diabetes mellitus (GDM), reduced IL-10 levels, and preterm birth." (PMID 22462002, 2012).
gestational diabetes (continued). "Recent studies indicate that OSA events positively correlate with systemic inflammation in both normal pregnancies and those with gestational diabetes mellitus (GDM), as indicated by higher circulating levels of TNF-α, IL-1β, IL-8, and IL-10." (PMID 38339130, 2024).
leukocytosis (17 papers, 2006 to 2025). "Other inflammation markers associated with poor prognosis after cell therapy include leukocytosis, lower levels of IL-10 (anti-inflammatory cytokine enhancing tissue repair), and higher levels of CD45 + inflammatory cells infiltrated in the wound." (PMID 40660298, 2025). "Studies show that KDSS patients often display neutrophilia, leukocytosis, elevated cytokine levels (IL-6, IL-10), hypoalbuminemia, and IVIG resistance, features that align with exaggerated systemic inflammation rather than a fundamentally different phenotype." (PMID 41204570, 2025). "One bout of high-intensity and prolonged exercise is known to induce acute leukocytosis and increase concentrations of cytokines such as IL-6 and IL-10 in the serum." (PMID 33139757, 2020). "In particular, the three forms of IL-10 were all successful in reducing intra-articular leukocytosis and the degree of synovitis, as well as normalizing cartilage matrix metabolism." (PMID 16704745, 2006). "Moreover, scorpion venoms could enhance the release of different inflammatory mediators which cause leukocytosis and raise the cytokines levels such as IL1b, IL6, IL8, IL10, TNFa and NO." (PMID 29367926, 2017). "Our results reproduced these findings, since leukocytosis and an increase in both IL-6 and IL-10 post-race was found regardless of LPS stimulation." (PMID 33139757, 2020). "IL-10 knockout mice have reduced viral reactivation from splenocytes but an increase in splenic weight and leukocytosis at 15 dpi, unlike the infected stat3f/f;CD19Cre/+ mice." (PMID 27486189, 2016). "IL‐10 showed negative correlations with the rest inflammatory markers on the 3rd day (WBC, CRP, ESR, ANC, NLR, and IL‐6), suggesting attenuating effect on IL‐6 levels, but also possible effect on leukocytosis reduction (by decreasing WBC, ANC, and NLR)." (PMID 35762501, 2023).
metastatic disease (17 papers, 2013 to 2025). "IL-10 receptor-α (IL10RA), which encodes a subunit of a receptor activated by the potent antiinflammatory cytokine IL-10, was significantly upregulated in myeloid cells of metastatic tumors, tumor-adjacent bone marrow, and premetastatic niche bone marrow." (PMID 40875516, 2025). "A tendency for an increased concentration of IL-4, IL-10 and IL-13 in blood plasma of patients with metastatic disease was evident." (PMID 39456247, 2024). "A gradually increased CSF1R from the inner tumors to the invasive fronts to the metastatic tumors was seen, whereas a trend of a decrease in IL-10 and IFNG was noted from the inner tumors to the invasive fronts to the metastatic tumors." (PMID 37586318, 2023). "Immunization at day 7 with C57BL/6 PBMCs resulted in a decrease in Tregs to 10.0 ± 2.9% and 14 ± 3.2 in spleen and metastatic tumour, respectively and a decrease serum IL-10/IL-2 ratio." (PMID 31683642, 2019). "miR-18a treatment led to increasing percentages of F4/80+IFNγ+, F4/80+IL-12+, F4/80+CD80+, and decreasing percentages of F4/80+ transforming growth factor beta (TGFβ)+, F4/80+CD206+ and F4/80+ IL-10+ detected in the liver metastatic tumor bearing mice." (PMID 27028860, 2016). "In the xenograft experiment in mice, tumors with high HLA-E expression grew rapidly and expressed high levels of IL-10 and TGF-β in plasma and tumor tissue and were associated with metastatic disease in bone marrow." (PMID 27322426, 2016). "Quantitative RT-PCR further confirmed that ICAM-1 deficiency significantly upregulated mRNA levels of IL-10, TGF-β, chemokine (C–C motif) ligand 17 (CCL17), CCL22 (M2-specific cytokines or chemokines) in hepatic metastatic tumors." (PMID 26068788, 2015). "Additionally, the negative regulator of cytokine signaling SOCS3, which acts downstream of IL-10 signaling, was also significantly upregulated in myeloid cells from metastatic tumors." (PMID 40875516, 2025). "Literature data support the conclusion that IL-10 production within the TME, principally in metastatic tumors, is a common process able to sustain cancer progression and resistance to therapies." (PMID 37835437, 2023). "Increased IL-10 and TGF-β levels were detected in plasma and tumor tissue from NB-Ehigh mice, as well as the increased metastatic diseases in the bone marrow." (PMID 27322426, 2016). "We found that the expression of M2-specific cytokines such as interleukin (IL)-13, IL-10, and transforming growth factor-β (TGF-β) was markedly increased in hepatic metastatic tumors of ICAM-1−/− mice compared with that in WT mice." (PMID 26068788, 2015). "Poor prognosis and metastatic tumors show obvious immune tolerance/immune escape features, including an increased proportion of M2 macrophages and DC2 cells and increased Th2 cells as well as high production of IL-10 and TGF-β among other characteristics of Treg cells." (PMID 37538794, 2023). "Although there is limited literature available on this specific relationship, one possible hypothesis is that elevated levels of IL-10 in non-metastatic tumours may contribute to the subsequent transition to metastatic disease, ultimately resulting in poorer survival outcomes." (PMID 39342063, 2024).
ovarian tumor (17 papers, 2007 to 2023). "It is possible that GRP78 may be associated with increased secretion of IL-10 by ovarian tumors and may expose NK cells homing to the tumor (intra-tumoral) as well as in the tumor vicinity." (PMID 36830840, 2023). "Another study defined IL-10 as a fundamental modulator of MDSCs within the ovarian tumor microenvironment, blockade of the IL-10 signaling network results in the alleviation of MDSCs-mediated immunosuppression." (PMID 35280697, 2022). "We found that the IL-10 level in ascites fluid was significantly higher for patients with serous OC than for those with LMP ovarian tumors, consistent with a previous report of high levels of IL-10 in ascites fluid of OC patients." (PMID 36056141, 2022). "IL-10 also acts as a critical regulator of the PD-1/PD-L1 axis for immunosuppression in the ovarian tumour microenvironment." (PMID 34930387, 2021). "In a mouse ovarian tumor model, PD-1 expression on TI DCs is demonstrated to be regulated by IL-10 cytokine." (PMID 34901012, 2021). "TAMs are recruited at ovarian tumor sites, and IL-6, IL-10, transforming growth factor (TGF)-β promote their differentiation in M2 macrophages, associated with tumor invasiveness, spread, and angiogenesis." (PMID 34503248, 2021). "IL10 along with PD-1 exhibited an anti-tumor response in ID8 ovarian tumor bearing mice, which leads to a decrease in tumor mass and a significant increase in survival." (PMID 30326660, 2018). "Similar to the ID8 mouse ovarian tumor model, we observed that patients who demonstrated strong anti-tumor T cell responses also showed less peripheral Treg cells and reductions of IL-10 in the sera following immunization." (PMID 26343191, 2015). "CREB is widely recognized to induce IL-10 expression, which is elevated in ovarian tumor ascites and is a mechanism of suppression by ovarian tumor-associated CD14+ cells." (PMID 26343197, 2015). "It is possible that ovarian tumors might have maintained persistent expression of IL-10 by increasing the expression of GRP78 and exhausting NK cells by inducing CISH expression and, thus, evading NK cell recognition." (PMID 36830840, 2023). "Ovarian tumors have been reported to secrete cytokines including IL-10 and IL-15." (PMID 36830840, 2023). "The goal of this study was to examine whether the population of CISH-expressing NK cells increased in ovarian tumors during OVCA development and progression and whether CISH-expression was associated with GRP78 and IL-10 levels." (PMID 36830840, 2023). "Therefore, a combination therapy of PD-1 therapy and IL-10 neutralization makes resistant tumors sensitive to PD-1 therapy in a mouse ovarian tumor model." (PMID 34901012, 2021). "In addition, IL-10 and indoleamine 2, 3-dioxygenase (IDO) were reported to promote immune evasion by ovarian tumor-associated macrophages." (PMID 31829231, 2019). "Macrophages and monocytes in the ovarian tumor may exhibit polarization to an M2, protumor, and immunosuppressive state, under the influence of colony-stimulating factor (CSF), IL-4, IL-13, IL-10, TGF-β and other soluble molecules." (PMID 30200478, 2018). "The aim of the present study was to determine whether differences exist in immunohistochemical staining of cytokines, TNF-α and interleukin-10 (IL-10) between benign tumors and malignant primary ovarian tumors." (PMID 25624918, 2015). "Our group and others have shown that ovarian tumors produced IL-10 and TGF-β, thus it is reasonable to suggest that HOCl-oxidation and not UVB-irradiation or repeat freeze-thaw cycles might have helped to inactivate these suppressive cytokines in the whole tumor cell lysate." (PMID 26343191, 2015). "Similar to our results, Coffelt and colleagues reported that ovarian tumor-derived leucine, leucine-37 recruits MSCs to the tumor microenvironment and stimulated MSCs secreted larger amounts of pro-angiogenic factors including IL-1 receptor antagonist, IL-6, IL-10 and VEGF to support angiogenesis." (PMID 23763837, 2013).